ALG6 (ALG6 alpha-1,3-glucosyltransferase)
Description:
Dolichyl pyrophosphate Man9GlcNAc2 alpha-1,3-glucosyltransferase that operates in the biosynthetic pathway of dolichol-linked oligosaccharides, the glycan precursors employed in protein asparagine (N)-glycosylation. The assembly of dolichol-linked oligosaccharides begins on the cytosolic side of the endoplasmic reticulum membrane and finishes in its lumen. The sequential addition of sugars to dolichol pyrophosphate produces dolichol-linked oligosaccharides containing fourteen sugars, including two GlcNAcs, nine mannoses and three glucoses. Once assembled, the oligosaccharide is transferred from the lipid to nascent proteins by oligosaccharyltransferases. In the lumen of the endoplasmic reticulum, adds the first glucose residue from dolichyl phosphate glucose (Dol-P-Glc) onto the lipid-linked oligosaccharide intermediate Man(9)GlcNAc(2)-PP-Dol to produce Glc(1)Man(9)GlcNAc(2)-PP-Dol. Glc(1)Man(9)GlcNAc(2)-PP-Dol is a substrate for ALG8, the following enzyme in the biosynthetic pathway.
Synonyms: CDG1C
Tractability: Antibody: UniProt predicts a signal peptide or a membrane-spanning region. PROTAC: ubiquitination databases record sites on it; its protein half-life has been measured.
Gene: Protein-coding gene on chromosome 1 (63,367,575 to 63,438,553, forward strand). Ensembl gene ENSG00000088035.
Subcellular location: Endoplasmic reticulum membrane
Subcellular location (Human Protein Atlas): Endoplasmic reticulum
Pathways (Reactome):
Disease: Defective ALG6 causes CDG-1c
Metabolism of proteins: Biosynthesis of the N-glycan precursor (dolichol lipid-linked oligosaccharide, LLO) and transfer to a nascent protein
Gene Ontology:
Molecular function: dolichyl pyrophosphate Man9GlcNAc2 alpha-1,3-glucosyltransferase activity; glucosyltransferase activity; protein binding; dolichyl-phosphate-glucose-glycolipid alpha-glucosyltransferase activity; hexosyltransferase activity
Biological process: dolichol-linked oligosaccharide biosynthetic process; protein N-linked glycosylation
Cellular component: membrane; endoplasmic reticulum membrane; lumenal side of endoplasmic reticulum membrane
Genetic constraint (gnomAD): Loss-of-function variants: 23 observed, 36.51 expected, observed/expected ratio (o/e) 0.63, 90% interval 0.45 to 0.89. The upper end of that interval is the gene's LOEUF score, 0.89, which puts it in group 3 of 6, group 1 being the genes least tolerant of losing a copy. Missense variants: 365 observed, 440.94 expected, observed/expected ratio (o/e) 0.83, 90% interval 0.76 to 0.9. Synonymous variants: 133 observed, 154.29 expected, observed/expected ratio (o/e) 0.86, 90% interval 0.75 to 1.
Gene-disease validity (ClinGen):
ClinGen rates the evidence that ALG6 causes each of these diseases.
ALG6-congenital disorder of glycosylation 1C (autosomal recessive): Definitive. A form of congenital disorders of N-linked glycosylation characterized by feeding problems, mild-to-moderate neurologic involvement with hypotonia, poor head control, developmental delay, ataxia, strabismus, and seizures, ranging from febrile convulsions to epilepsy.
cystic kidney disease (autosomal dominant): Limited. A congenital or acquired kidney disorder characterized by the presence of renal cysts.
Homologues: Orthologues: chimpanzee ALG6 (99% identical), macaque ALG6 (97% identical), dog ALG6 (94% identical), pig ALG6 (94% identical), rabbit ALG6 (92% identical), mouse Alg6 (84% identical), rat Alg6 (78% identical), guinea pig ALG6 (77% identical), tropical clawed frog alg6 (65% identical), zebrafish alg6 (61% identical), Drosophila melanogaster gny (42% identical), Caenorhabditis elegans algn-6 (36% identical). Paralogues in human: ALG8 (26% identical).
Diseases named in the same sentence as ALG6 in open-access papers:
ALG6 is named in the same sentence as 45 diseases in open-access papers, as found by Europe PMC text mining. Sharing a sentence is not in itself a finding about the gene and the disease. The quoted sentences say what the papers report.
congenital disorder of glycosylation (3 papers, 2014 to 2022). Congenital disorder of glycosylation (CDG) is a fast growing group of inborn errors of metabolism characterized by defective activity of enzymes that participate in glycosylation (modification of proteins and other macromolecules by adding and processing of oligosaccharide side chains). "In patients with congenital disorder of glycosylation (CDG) associated with mutations in the ALG6 gene, which encodes Man9GlcNAc2-PP-dolichol: dolichol-Glc glucosyltransferase, Man9GlcNAc2-PP-dolichol is poorly glucosylated and inefficient protein N-glycosylation ensues." (PMID 32188137, 2020). "Patients with pathogenic ALG6 variants have abnormal accumulation of Man9GlcNAc2-P-P-Dol and hypoglycosylation of proteins which contribute to autosomal recessive congenital disorder of glycosylation (CDG) Type Ic (or ALG6-CDG)." (PMID 35911904, 2022).
developmental delay (3 papers, 2021 to 2023). "In contrast to the severely affected ALG6-CDG patients (presenting with multi-organ involvement including developmental delay and multiple neurological symptoms), our patients presented with a phenotype of multiple kidney cysts and/or liver cysts." (PMID 36807342, 2023). "ALG6-CDG is typically characterized by developmental delay, seizures and speech disabilities." (PMID 35911904, 2022).
cutaneous melanoma (2 papers, 2021 to 2025). A primary melanoma arising from atypical melanocytes in the skin. "The ALG6 single-nucleotide polymorphism (SNP) is a potential prognostic biomarker for cutaneous melanoma and is likely through modulating gene expression." (PMID 34692502, 2021). "suggests that variants in ALG6, as part of the glycosylation pathway, could serve as potential prognostic biomarkers for cutaneous melanoma." (PMID 40963867, 2025).
epilepsy (2 papers, 2021 to 2023). A brain disorder characterized by episodes of abnormally increased neuronal discharge resulting in transient episodes of sensory or motor neurological dysfunction, or psychic dysfunction. "The patient with a genetic defect in ALG6 shows strong glycosylation abnormalities, as well as severe clinical symptoms such as mental disorders, motoric retardation, seizures, and epilepsy." (PMID 36768261, 2023).
Ataxia (1 paper, 2021). Ataxia refers to impaired coordination of voluntary muscle movement. "The disease should, however, be included in the differential diagnosis, especially in the evaluation of patients with seizures, ataxia, areflexia, developmental delay (ALG6-CDG) or be evaluated in individuals diagnosed with PMM2-CDG." (PMID 33440761, 2021).
autoimmune disease (1 paper, 2020). A disorder resulting from loss of function or tissue destruction of an organ or multiple organs, arising from humoral or cellular immune responses of the individual to their own tissue constituents. "Besides PMM2-CDG, three reports of autoimmune diseases have been associated with the ALG gene family (eosinophilic esophagitis in an ALG1-CDG patient with a severe phenotype, and psoriasis in an ALG3-CDG and an ALG6-CDG patient)." (PMID 32635232, 2020).
autosomal dominant polycystic kidney (1 paper, 2023). "The phenotype in the genetically unsolved polycystic kidney and liver patients we identified to carry ALG6 variants is relatively mild, in many cases liver predominant and asymptomatic, consistent with the phenotype described for patients carrying a heterozygous ALG8 or ALG9 pathogenic variant." (PMID 36807342, 2023). "ALG6, similarly to established polycystic kidney and liver disease gene ALG8, is a member of the α3-glucosyltransferase family." (PMID 36807342, 2023). "Biological validation will be necessary to finally determine if ALG6 is a disease gene for autosomal dominant polycystic kidney and liver phenotypes." (PMID 36807342, 2023).
buphthalmia (1 paper, 2022). "Eyes abnormalities such as glaucoma and buphthalmia were present in SRD5A3 patients, and optic nerve/disc alterations are a relatively nonspecific finding, present in ALG6‐, DPM1‐, MPDU‐, and SRD5A3‐CDG." (PMID 35279850, 2022).
colon adenocarcinoma (1 paper, 2020). "However, the higher expression levels of ALG6 were associated with a better survival in colon adenocarcinoma (p = 0.028) and lung squamous cell carcinoma patients (p = 0.038), respectively." (PMID 31991610, 2020). "Although the present study suggested that the expression of ALG6 seemed not to have a significant effect on CM survival, a high ALG6 expression was associated with a better overall survival (OS) in colon adenocarcinoma and lung squamous cell carcinoma patients." (PMID 31991610, 2020).
cone-rod degeneration (1 paper, 2024). "In the eleven patients analyzed here, clinical diagnoses of RP (in most patients) versus cone-rod degeneration (CRD) (in one family) did not correlate with the ALG6 variant, and limited ERG findings were not informative." (PMID 38256083, 2024).
Congenital glycosylation disorder, type Ic (1 paper, 2019). "Congenital glycosylation disorder, type Ic (OMIM # 603147), caused by the homozygous mutation in the ALG6 gene, leads to psychomotor retardation with delayed walking and speech, hypotonia, seizures, mild to severe ID and sometimes enteropathy." (PMID 30866944, 2019).
cyst (1 paper, 2023). A sac-like closed membranous structure that may be empty or contain fluid or amorphous material. "We realize that based on the present literature alone, ALG6 would be a candidate gene for the cyst phenotype in SAMPLE6." (PMID 36807342, 2023).
cystic kidney (1 paper, 2023). "Applying KidneyNetwork to a group of undiagnosed cases identified ALG6 as a candidate gene in cystic kidney and liver disease." (PMID 36807342, 2023). "We strengthen this plausibility by identifying ALG6 variants in several cystic kidney and liver disease cases without alternative genetic explanation." (PMID 36807342, 2023).
dilated cardiomyopathy (1 paper, 2010). Cardiomyopathy which is characterized by dilation and contractile dysfunction of the left and right ventricles. "In conclusion, we present the first case of ALG6-CDG associated with mild dilated cardiomyopathy due to a novel mutation in the ALG-6 gene." (PMID 20398363, 2010). "Here we report a Saudi child with ALG6-CDG and dilated cardiomyopathy caused by a novel mutation." (PMID 20398363, 2010). "However, in addition, he shows dilated cardiomyopathy, a feature previously not reported in ALG6-CDG." (PMID 20398363, 2010).
gastroesophageal reflux (1 paper, 2022). "Dysphagia and/or gastroesophageal reflux was present in ALG1‐, ALG6‐, ALG11‐, ALG12‐, DPM1‐, and DOLK‐CDG." (PMID 35279850, 2022).
glioma (1 paper, 2022). A benign or malignant brain and spinal cord tumor that arises from glial cells (astrocytes, oligodendrocytes, ependymal cells). "The top were GALNT3, ALG6 and B3GNT7, which displayed a p < 1 × 10−9 in the low-grade glioma (LGG) cohort." (PMID 35565254, 2022).
Hypoglycemia (1 paper, 2020). A decreased concentration of glucose in the blood. "Other CDG in which hypoglycemia has been reported are DOLK‐CDG, ALG6‐CDG, ALG3‐CDG, and ALG12‐CDG." (PMID 32071842, 2020).
liver cysts (1 paper, 2023). "The intersection of prioritized genes with genes carrying rare variants in a patient with kidney and liver cysts identified ALG6 as plausible candidate gene." (PMID 36807342, 2023). "ALG6 strongly resembles ALG8 which has been implicated in kidney and liver cyst phenotypes, and according to KidneyNetwork, ALG6 and ALG8 are highly co-regulated (z-score = 8.59)." (PMID 36807342, 2023). "In one patient (SAMPLE6), manual curation of this list identified ALG6 (ALG6 alpha-1,3-glucosyltransferase) as a potential candidate gene to explain the patient’s kidney and liver cysts." (PMID 36807342, 2023). "Using KidneyNetwork, we highlight ALG6 as candidate gene for kidney and/or liver cysts." (PMID 36807342, 2023). "We also investigated the 100,000 Genomes Project dataset and contacted collaborators which identified three additional patients with kidney and/or liver cysts carrying a heterozygous potentially deleterious variant in ALG6, without an alternative genetic explanation." (PMID 36807342, 2023). "Interestingly, while kidney or liver cysts have been described, among multi-organ involvement in fetuses or children with ALG9-CDG or infrequently in ALG8-CDG, cysts have not been described for ALG6-CDG." (PMID 36807342, 2023).
melanoma (1 paper, 2020). A malignant, usually aggressive tumor composed of atypical, neoplastic melanocytes. "Because of the close relationship established between ALG6 and N-linked glycosylation and melanoma cell activity, genetic variation in ALG6 is likely to play a role in CM progression and prognosis." (PMID 31991610, 2020). "Although the ALG6 gene malfunction may play a role in the poor prognosis of melanoma, we also showed that the mutation rate of ALG6 in melanoma tissues was less than 2.56%, and thus the overall expression levels of ALG6 in melanoma tissues are more likely to be affected by SNPs." (PMID 31991610, 2020). "We found that the expression levels of ALG6 seemed not to be substantially associated with melanoma survival (p = 0.671)." (PMID 31991610, 2020). "In a previous animal study, however, we noted that knockdown of the mouse Alg6 gene increased melanoma lung metastasis without affecting primary tumor growth, which may lead to a shorter survival." (PMID 31991610, 2020).
tumor (3 papers, 2020 to 2025). "Nevertheless, the specific mechanistic role of ALG6 in tumor biology remains to be elucidated and warrants further investigation." (PMID 40963867, 2025).
infection (1 paper, 2013). The state of being infected such as from the introduction of a foreign agent such as serum, vaccine, antigenic substance or organism. "Conversion from incident to older infection status among these 7 algorithms occurred first for Alg3 (gp41 band ≤0.5), tightly followed by Alg3.1 (gp41≤1) and Alg5 (p24≤0.5), Alg6 (p17≤0.5), Alg14, Alg2 (gp120≤1) and finally Alg4 (p31 = 0)." (PMID 23990968, 2013).
skeletal dysplasia (1 paper, 2021). Any Mendelian diseases that affects growth and development of the skeleton. "Contrary to PMM2-CDG, skeletal dysplasia was well characterized in other CDGs, including ALG12-CDG, ALG3-CDG, ALG9-CDG, ALG6-CDG, PGM3-CDG, CSGALNACT1-CDG, SLC35D1-CDG and TMEM165-CDG." (PMID 34441372, 2021). "Contrary to PMM2-CDG, all remaining CDG, including ALG12-CDG, ALG3-CDG, ALG9-CDG, ALG6-CDG, PGM3-CDG, CSGALNACT1-CDG, SLC35D1-CDG and TMEM-165, are characterized by well-defined skeletal dysplasia." (PMID 34441372, 2021). "There is a group of CDGs, including ALG12-CDG, ALG3-CDG, ALG9-CDG, ALG6-CDG, PGM3-CDG, CSGALNACT1-CDG, SLC35D1-CDG, and TMEM-165 with well-defined skeletal dysplasia." (PMID 34441372, 2021).
ALG6 also shares sentences with these, for which no sentence is quoted: brachydactyly (1 paper); cryptorchidism (1); enteropathy (1); eosinophilic esophagitis (1); fructose intolerance (1); glaucoma (1); Hepatic steatosis (1); Kabuki syndrome (1); Kidney Cyst (1); kidney disease (1); kidney stones (1); Lesch-Nyhan syndrome (1); liver disease (1); lung squamous cell carcinoma (1); mental disorder (1); metabolic disorder (1); mucopolysaccharidosis type 2 (1); neuronal ceroid lipofuscinosis (1); neuropathy (1); psoriasis (1); retinal degeneration (1); scoliosis (1); Stroke (1).